PTBP3 (polypyrimidine tract binding protein 3)
Description:
RNA-binding protein that mediates pre-mRNA alternative splicing regulation. Plays a role in the regulation of cell proliferation, differentiation and migration. Positive regulator of EPO-dependent erythropoiesis. Participates in cell differentiation regulation by repressing tissue-specific exons. Promotes FAS exon 6 skipping. Binds RNA, preferentially to both poly(G) and poly(U).
Synonyms: Rod1; DKFZp781I1117
Tractability: PROTAC: UniProt records ubiquitination sites on it; ubiquitination databases record sites on it; its protein half-life has been measured.
Gene: Protein-coding gene on chromosome 9 (112,215,071 to 112,333,695, reverse strand). Ensembl gene ENSG00000119314.
Subcellular location (Human Protein Atlas): Nucleoplasm
Gene Ontology:
Molecular function: RNA binding; nucleic acid binding
Biological process: negative regulation of RNA splicing; anatomical structure morphogenesis; mRNA processing; regulation of cell differentiation
Cellular component: nucleus
Genetic constraint (gnomAD): Loss-of-function variants: 15 observed, 46.35 expected, observed/expected ratio (o/e) 0.32, 90% interval 0.22 to 0.5. The upper end of that interval is the gene's LOEUF score, 0.5, which puts it in group 2 of 6, group 1 being the genes least tolerant of losing a copy. Missense variants: 468 observed, 577.54 expected, observed/expected ratio (o/e) 0.81, 90% interval 0.75 to 0.88. Synonymous variants: 170 observed, 202.99 expected, observed/expected ratio (o/e) 0.84, 90% interval 0.74 to 0.95.
Homologues: Orthologues: chimpanzee PTBP3 (99% identical), macaque PTBP3 (98% identical), rabbit PTBP3 (98% identical), dog PTBP3 (96% identical), guinea pig PTBP3 (96% identical), pig PTBP3 (96% identical), mouse Ptbp3 (95% identical), rat Ptbp3 (95% identical), tropical clawed frog ptbp3 (86% identical), zebrafish ptbp3 (81% identical), Drosophila melanogaster heph (55% identical), Caenorhabditis elegans ptb-1 (48% identical). Paralogues in human: PTBP1 (78% identical), PTBP2 (69% identical), HNRNPL (28% identical), HNRNPLL (26% identical), RBM20 (22% identical).
Diseases named in the same sentence as PTBP3 in open-access papers:
PTBP3 is named in the same sentence as 59 diseases in open-access papers, as found by Europe PMC text mining. Sharing a sentence is not in itself a finding about the gene and the disease. The quoted sentences say what the papers report.
breast carcinoma (21 papers, 2018 to 2023). "Recent studies have shown that PTBP3 promotes epithelial–mesenchymal transition in breast cancer through the regulation of ZEB1 mRNA stability." (PMID 37633911, 2023). "For instance, lncRNA BCRT1, which acts as a tumour promoter in breast cancer, can competitively bind to miR-1303 to prevent the degradation of its target gene PTBP3." (PMID 37752588, 2023). "Previous studies have shown that PTBP3 is dysregulated and promotes the progression of numerous cancers, including breast cancer, hepatocellular cancer, gastric cancer and CRC." (PMID 35136024, 2022). "Exosomal lncRNA breast cancer-related transcript 1 (BCRT1) induces M2 macrophage polarization by activating miR-1303/polypyrimidine tract binding protein 3 (PTBP3) axis in breast cancer." (PMID 36153596, 2022). "In the lncRNA BCRT1/miR-1303/PTBP3 axis, polypyrimidine tract binding protein 3 (PTBP3) promotes breast cancer, and the expression of lncRNA BCRT1 in breast cancer tissues is significantly increased, which is related to the poor prognosis of patients." (PMID 35145526, 2022). "PTBP3 expression is positively correlated with lymph node metastasis and poor 5-year survival in patients with breast cancer." (PMID 35359851, 2022). "LncRNA BCRT1 acts as a ceRNA for miRNA-1303 which targets Poly pyrimidine tract-binding protein 3 (PTBP3), thus protecting PTBP3 from degradation and promoting breast cancer progression." (PMID 36207500, 2022). "The lncRNA BCRT1 acts as ceRNA and regulates polypyrimidine tract binding protein 3 (PTBP3) expression by targeting miR-1303 in breast carcinoma." (PMID 35800083, 2022). "PTBP3 is upregulated in breast cancer and regulates ZEB1 mRNA stability to promote epithelial-mesenchymal transition in BRCA." (PMID 36203873, 2022). "For instance, lncRNA BCRT1 was reported to competitively bind with miR-1303 to prevent the degradation of PTBP3, which induced the progression of breast cancer." (PMID 35371339, 2022). "LncRNA BCRT1 stabilizes polypyrimidine tract-binding protein 3 (PTBP3) through sponging miR-1303 and promotes breast cancer progression." (PMID 34830378, 2021). "In breast cancer patients, lymph node metastasis, histological grade, TNM staging, and poor prognosis are all associated with high levels of PTBP3 expression." (PMID 32477006, 2020). "Overexpression of PTBP3 promotes breast cancer cell proliferation and epithelial mesenchymal transition (EMT)." (PMID 32477006, 2020). "Previous study showed PTBP3 protein level was increased in lung squamous cell carcinomas, breast cancer, and gastric carcinoma." (PMID 32477006, 2020). "The findings were consistent with previous studies about PTBP3 promoting cell growth in breast cancer and gastric cancer." (PMID 31291975, 2019). "Recently, we have discovered that PTBP3 was located both in nuclear and cytoplasm; and that PTBP3 promoted breast cancer EMT and metastasis by repressing ZEB1 mRNA degradation." (PMID 31291975, 2019). "LncRNA BCRT1 promotes breast cancer progression by targeting miR-1303/PTBP3 axis." (PMID 35477447, 2022). "Additionally, PTBP3 overexpression was found in hepatocellular cancer, gastric cancer, and breast cancer and was correlated with a poor clinical prognosis, suggesting that PTBP3 may serve as an oncogene in multiple cancers." (PMID 35136024, 2022). "Previous studies demonstrated that PTBP3 enhances the invasion and metastasis of breast cancer and regulates the expression of drug resistance proteins in gastric cancer, suggesting that PTBP3 may serve as a potential novel therapeutic target for gastric cancer." (PMID 36203873, 2022). "The lncRNA BCRT1/miR-1303/PTBP3 and lncRNA Xist/miR-101-3p/KLF6/C/EBPα can regulate the progression of breast cancer." (PMID 35145526, 2022).
breast carcinoma (continued). "The exosomal LncRNA BCRT1 is significantly upregulated in breast cancer tissues and positively correlates with tumor growth, metastasis, and poor prognosis in breast cancer patients by functioning through the HIF-1α/lncRNA BCRT1/miR-1303/PTBP3 pathways." (PMID 36233088, 2022). "PTBP3, a member of the PTB family, has been reported to be involved in tumorigenesis and progression, such as in lung cancer, pancreatic cancer, breast cancer, gastric cancer, colorectal cancer, and hepatocellular carcinoma." (PMID 35359851, 2022). "In addition, PTBP3 can regulate the expression of ZEB1 (epithelial-mesenchymal transition regulatory transcription factor) and promotes tumour cell invasive growth and metastasis in breast cancer." (PMID 35359851, 2022). "Studies conducted in breast cancer have shown that lncRNA BCRT1 acts as a molecular sponge of miR-1303, negatively regulates the expression of miR-1303, and upregulates the expression of PTBP3 via exocrine, which, in turn, promotes the development of breast cancer." (PMID 36035993, 2022).
gastric cancer (17 papers, 2018 to 2025). A primary or metastatic malignant neoplasm involving the stomach. "Survival analysis of PTBP3 expression in peritoneal metastases of gastric cancer revealed that high expression was associated with poorer prognosis." (PMID 40270362, 2025). "To elucidate the biological processes associated with the metastatic progression of gastric cancer cells mediated by PTBP3 splicing targets, we performed KEGG pathway enrichment analysis on gene sets exhibiting differential alternative splicing events." (PMID 40270362, 2025). "Thus, the loss of feedback regulation among PTBP3, Id1, and Hes1 in gastric cancer cells may be one of the causes of inhibited differentiation and malignant proliferation of these cells." (PMID 32974175, 2020). "Collectively, these findings demonstrate that the splicing factor PTBP3 is significantly upregulated in tumor cells of peritoneal metastatic lesions in gastric cancer." (PMID 40270362, 2025). "A shortened protein produced by PTBP3‐triggered exon skipping in COX11 allows cancer cells to evade cuprotosis in gastric cancer." (PMID 41399527, 2025). "In gastric cancer, circRNA‐mediated pathways drive expression of oncogenic RON variants, and PTBP3‐mediated skipping of COX11 exons facilitates resistance to cuproptosis." (PMID 41399527, 2025). "Through our analyses, we determined that PTBP3 is a crucial splicing factor involved in the progression of gastric cancer peritoneal metastasis, participating in numerous alternative splicing events." (PMID 40270362, 2025). "In conclusion, we believe that PTBP3 plays a crucial role in promoting peritoneal metastasis of gastric cancer, and therefore, we selected PTBP3 as the target molecule for further investigation." (PMID 40270362, 2025). "In contrast, in peritoneal metastatic gastric cancer organoids, PTBP3 knockdown reduced organoid diameter and viability." (PMID 40270362, 2025). "In conclusion, our research identifies PTBP3 as an oncogenic splicing factor and a prognostic marker for gastric cancer peritoneal metastasis." (PMID 40270362, 2025). "In this study, PTBP3 is found to be significantly overexpressed in peritoneal metastatic tissues of gastric cancer compared to primary tumor tissues, and higher PTBP3 expression correlates with poorer prognosis." (PMID 40270362, 2025). "These experimental results confirm that in the established animal model of peritoneal metastasis from gastric cancer cells, PTBP3 regulates COX11 alternative splicing, significantly impacting tumor metastatic progression." (PMID 40270362, 2025). "Taken together, these functional experiments confirm that PTBP3 mediates the invasive and proliferative activities of gastric cancer cells and organoids, thereby promoting gastric cancer metastasis." (PMID 40270362, 2025). "Further investigations revealed that PTBP3 promotes invasive growth in gastric cancer cells and organoids, driving tumor progression in a peritoneal injection model of gastric cancer cells." (PMID 40270362, 2025). "Our research has shown that the splicing factor PTBP3 is overexpressed in gastric cancer peritoneal metastasis tissues." (PMID 40270362, 2025). "The results demonstrated that the addition of ASOs to organoids overexpressing PTBP3 significantly reduced organoid viability and compromised the invasive growth potential of organoids derived from primary gastric cancer tissues." (PMID 40270362, 2025). "Polypyrimidine tract-binding protein 3 (PTBP3) increases the migration and invasion ability of gastric cancer cells through mediating CAV1 selective splicing." (PMID 39726754, 2024). "Other studies have revealed that PTBP3 knockdown in gastric cancer cells inhibited the phosphorylation of Akt, which has also been demonstrated to be involved in HCC growth and metastasis." (PMID 37633911, 2023). "It has been reported in the literature that PTBP1 can be used as a biomarker for poor prognosis in bladder cancer, and PTBP3 as a therapeutic target for gastric cancer." (PMID 36203873, 2022).
gastric cancer (continued). "Inhibition of PTBP3 induces apoptosis and cell cycle arrest, and enhances the cytotoxicity of 5- fluorouracil in gastric cancer cells." (PMID 32117452, 2020). "In this study, we found that PTBP3 was upregulated in the poorly differentiated gastric cancer tissues." (PMID 32974175, 2020). "Kaplan–Meier survival analysis showed that gastric cancer patients with high PTBP3 expression had a worse outcome than those with low PTBP3 expression (P = 0.028)." (PMID 32974175, 2020). "In the present study, we found that PTBP3 was upregulated in the poorly differentiated gastric cancer tissues." (PMID 32974175, 2020). "In gastric cancer, PTBP3 contributes to the cancer metastasis by mediating CAV1 alternative splicing." (PMID 32117452, 2020). "MKN45 cells were induced to differentiate with NaBU and the expressions of Id1a, Id1b, PTBP3 and Hes1 (proteins closely related to the differentiation of gastric cancer cells) were detected." (PMID 32974175, 2020). "Immunohistochemistry analysis showed that PTBP3 was up-regulated in the poorly-differentiation of gastric cancer tissues." (PMID 32974175, 2020). "After testing the mRNA expression of PTBP3 in tissue samples from gastric cancer patients, we found PTBP3 level in the poorly-differentiation of gastric cancer tissues were significantly higher." (PMID 32974175, 2020). "In gastric cancer cells, the regulatory effect of PTBP3 on alternative splicing of the Id1 gene was investigated." (PMID 32974175, 2020). "PTBP3 has also been found to play important roles in lung adenocarcinoma, glioblastoma multiforme, squamous cell carcinoma, and gastric cancer." (PMID 32117452, 2020). "To further confirm these results and clarify the clinical significance of PTBP3, we first used immunohistochemistry to screen the expression of PTBP3 in adjacent normal tissues, well and poorly-differentiation of gastric cancer tissues by immunohistochemistry." (PMID 32974175, 2020). "Our previous study also indicated that after PTBP3 silencing in gastric cancer cells, the cells showed the characteristics of differentiation, the nucleus/cytoplasmic ratio decreased, the nucleus became regular, and the nucleolus decreased." (PMID 32974175, 2020). "Our previous study indicated that the expression of PTBP3 in gastric cancer was higher than in normal gastric mucosa, and it inhibited the differentiation of MKN45 cells and promoted their proliferation." (PMID 32974175, 2020). "A prooncogenic role for PTBP3 has also been discovered in governing gastric cancer cell cycle and growth." (PMID 31291975, 2019). "The cell wound-healing assay showed the invasive ability of gastric cancer cells with PTBP3 knockdown and CAV1α inhibition was promoted." (PMID 29752441, 2018). "In this study, we found that PTBP3 was upregulated in the gastric cancer tissues of patients with lymph node metastasis." (PMID 29752441, 2018). "PTBP3 expression was first analysed in 375 gastric cancer tissues and 32 normal gastric tissues, and we found that PTBP3 was significantly upregulated in gastric cancer tissues." (PMID 29752441, 2018). "In the present study, we found PTBP3 to be upregulated in gastric cancer tissues of patients with lymph node metastasis." (PMID 29752441, 2018). "Here, to gain better insight into the function of PTBP3 in gastric carcinoma progression, we used MKN45 gastric cells as a major experimental system to directly explore the function of PTBP3 in gastric cancer tumour growth and metastasis." (PMID 29752441, 2018). "Taken together, these findings suggest that PTBP3 is upregulated in the gastric cancer tissues of patients with lymph node metastasis, and patients with high PTBP3 expression showed a high risk of lymph node metastasis." (PMID 29752441, 2018). "Kaplan–Meier survival analysis showed that lymph node metastasis in gastric cancer patients with high PTBP3 expression correlated with a worse outcome than lymph node metastasis in those with low PTBP3 expression (P = 0.035)." (PMID 29752441, 2018).
gastric cancer (continued). "Given that our data indicate that PTBP3 behaves as a ‘metastasis-promoter gene’ in gastric cancer, we next sought to determine the possible mechanisms for this observed phenotype." (PMID 29752441, 2018). "Although increasing evidence implicates PTBP3 in several cancers, its role in gastric cancer metastasis remains poorly explored." (PMID 29752441, 2018). "To confirm the function of PTBP3 on gastric cancer migration and invasion, we silenced PTBP3 in MKN45 and SGC7901 cells using pSilencer-PTBP3." (PMID 29752441, 2018). "To assess how PTBP3 expression contributes to the invasion and metastasis of gastric cancer, we next aimed to investigate the regulated genes of PTBP3 as an RNA-binding protein." (PMID 29752441, 2018). "We also selected MKN45 cells for lentiviral infection to establish control and PTBP3‐overexpressing cell lines, and SNU‐1 cells for plasmid transfection to create control and PTBP3‐knockout cell lines, based on PTBP3 expression levels in commonly used gastric cancer cell lines." (PMID 40270362, 2025). "Furthermore, clinical and pathological analysis of 102 primary gastric cancer cases demonstrated that high PTBP3 expression was positively correlated with both T stage and peritoneal metastasis, suggesting its potential role in disease progression." (PMID 40270362, 2025). "Our findings highlight PTBP3 as a crucial oncogenic splicing factor, and targeting the alternative splicing events regulated by PTBP3 could serve as an effective therapeutic strategy for peritoneal metastasis in gastric cancer." (PMID 40270362, 2025). "A correlation analysis between the percent splicing index (PSI) values of COX11 and PTBP3 protein expression levels was conducted on 20 gastric cancer peritoneal metastatic samples and 22 primary gastric cancer samples, revealing a significant correlation between these factors." (PMID 40270362, 2025). "The selective splicing of CAV1 mediates the PTBP3-promoted metastasis of gastric cancer." (PMID 39726754, 2024). "We found that the expression of PTBP3 was higher in gastric cancer than in normal gastric mucosa, inhibition of PTBP3 could induce apoptosis of gastric cancer cells and cell cycle arrest." (PMID 32974175, 2020). "Our previous study has shown that in gastric cancer tissues, PTBP3 protein was overexpressed." (PMID 32974175, 2020). "The results suggested that PTBP3 may have an effect on the proliferation and differentiation of gastric cancer cells." (PMID 32974175, 2020). "Moreover, GSEA comparing gastric cancer tumours with high expression and those with low expression of PTBP3 using TCGA and three independent GEO datasets showed a strong correlation between PTBP3 expression and the cell migration signalling pathway." (PMID 29752441, 2018). "To determine whether PTBP3 promotes gastric cancer migration and invasion, we overexpressed PTBP3 in MKN45 and SGC7901 cells using pcDNA-PTBP3." (PMID 29752441, 2018). "In summary, our findings provide experimental evidence that PTBP3 may function as a metastatic gene in gastric cancer by regulating CAV1 through alternative splicing." (PMID 29752441, 2018). "To test our hypothesis, we analysed the expression of PTBP3 and CAV1α in gastric cancer tissues from lymph node metastatic patients." (PMID 29752441, 2018). "However, the role of PTBP3 in gastric carcinoma tumour formation and metastasis remains poorly understood." (PMID 29752441, 2018). "Based on our observations on the metastatic function of PTBP3 in this study, intertwining with the importance of CAV1 in tumour metastasis, we questioned whether the metastasis function of PTBP3 in gastric cancer was attributed to its suppressive effect on CAV1α expression by alternative splicing." (PMID 29752441, 2018). "In addition, PTBP3 expression is upregulated in gastric cancer compared with that in normal gastric mucosa, a finding that may closely positively correlate with gastric carcinoma progression." (PMID 29752441, 2018).